STOML3 (stomatin like 3)
Description:
Required for the function of many mechanoreceptors. Modulate mechanotransduction channels and acid-sensing ion channels (ASIC) proteins. Potentiates PIEZO1 and PIEZO2 function by increasing their sensitivity to mechanical stimulations.
Synonyms: SRO; Epb7.2l
Tractability: Antibody: its Gene Ontology location is reachable by antibodies, with high confidence; UniProt places it where antibodies can reach, with medium confidence; UniProt predicts a signal peptide or a membrane-spanning region; the Human Protein Atlas places it where antibodies can reach.
Gene: Protein-coding gene on chromosome 13 (38,965,925 to 38,990,871, reverse strand). Ensembl gene ENSG00000133115.
Subcellular location: Cell membrane
Subcellular location (Human Protein Atlas): Plasma membrane
Pathways (Reactome):
Transport of small molecules: Stimuli-sensing channels
Gene Ontology:
Molecular function: protein binding; ion channel inhibitor activity
Cellular component: plasma membrane; cilium; membrane; membrane raft
Genetic constraint (gnomAD): Loss-of-function variants: 33 observed, 33.72 expected, observed/expected ratio (o/e) 0.98, 90% interval 0.74 to 1.31. The upper end of that interval is the gene's LOEUF score, 1.31, which puts it in group 5 of 6, group 1 being the genes least tolerant of losing a copy. Missense variants: 380 observed, 381.63 expected, observed/expected ratio (o/e) 1, 90% interval 0.92 to 1.08. Synonymous variants: 122 observed, 147.11 expected, observed/expected ratio (o/e) 0.83, 90% interval 0.71 to 0.96.
Homologues: Orthologues: chimpanzee STOML3 (100% identical), macaque STOML3 (98% identical), rabbit STOML3 (93% identical), dog STOML3 (93% identical), guinea pig STOML3 (93% identical), pig STOML3 (93% identical), rat Stoml3 (92% identical), mouse Stoml3 (91% identical), zebrafish stoml3b (60% identical), Caenorhabditis elegans sto-2 (57% identical), zebrafish stoml3a (56% identical), Drosophila melanogaster CG42540 (53% identical), and 1 more. Paralogues in human: STOM (64% identical), NPHS2 (43% identical), STOML1 (30% identical), STOML2 (29% identical).
Diseases named in the same sentence as STOML3 in open-access papers:
STOML3 is named in the same sentence as 8 diseases in open-access papers, as found by Europe PMC text mining. Sharing a sentence is not in itself a finding about the gene and the disease. The quoted sentences say what the papers report.
autism spectrum disorder (2 papers, 2021 to 2022). A spectrum of developmental disorders that includes autism, and Asperger syndrome. "In addition to schizophrenia, the genomic region around STOML3 has been associated with autism spectrum disorders as well as psychotic depression." (PMID 35342390, 2022).
schizophrenia (2 papers, 2021 to 2022). A major psychotic disorder characterized by abnormalities in the perception or expression of reality. "Furthermore rs77744003, a variant within the schizophrenia-related STOML3 gene, showed an interactive effect." (PMID 35342390, 2022).
neuroblastoma (1 paper, 2024). Neuroblastoma (NB) is the most common solid, extracranial childhood tumor. "Furthermore, a similar effect was observed in N2a neuroblastoma cells that express very low endogenous level of STOML3: overexpressing WT STOML3 strongly potentiated stretch-activated currents, whereas cholesterol-binding deficient mutant of STOML3 did not." (PMID 38333595, 2024).
kidney diseases (1 paper, 2025). "Stabilizing Podocin oligomers could help restore membrane integrity in kidney diseases, while disrupting oligomerization in other SPFH proteins—such as STOML3—might dampen mechanosensory responses and provide avenues for pain relief." (PMID 40796562, 2025).
STOML3 also shares sentences with these, for which no sentence is quoted: depression (2 papers); asthma (1); diabetic neuropathy (1); mood disorder (1).